EGFR (epidermal growth factor receptor)
Diseases named in the same sentence as EGFR in open-access papers (continued):
Sharing a sentence is not in itself a finding about the gene and the disease.
glioma (continued). "Glioma cells expressing EGFRvIII were found to recruit EGFR-WT-expressing cells and accelerate glioma tumorigenicity by up-regulating the expression levels of cytokines (e.g., interleukin 6 [IL6] and/or leukemia inhibitory factor)." (PMID 25992628, 2015). "The activation of the EGFR signaling pathway is involved in most of the malignant biological behaviors of glioma." (PMID 25644759, 2015). "pUS treatment prolonged the mean circulatory halftime of targeting MBs and enhanced the anti-tumor effect of EGFR antibodies in a human glioma model in mice." (PMID 25960704, 2015). "Among them, we found: members of the RTK superfamily involved in tumor growth, survival and angiogenesis of gliomas including epidermal growth factor receptor (EGFR), platelet-derived growth factor receptors (PDGFRs) and anaplasic lymphoma kinase (ALK)." (PMID 25360666, 2014). "The ODA14 tumour was selected after quantitative PCR screening of a series of gliomas for amplification of the EGFR,MET,MYC and PDGFRA genes, which are known to be recurrently amplified in these tumours." (PMID 25378339, 2014). "Some genes in this survival module were similarly implicated in the occurrence and development of glioma, such as ERBB2, ITGB3, EGFR, and MET." (PMID 24809850, 2014). "We have also previously shown COX-2 regulation by signaling pathways arising from epidermal growth factor receptor accepted to be important in glioma pathogenesis." (PMID 24659686, 2014). "Our model for the mechanism of action of SF1126 in glioma cells shows that ERK can be stimulated downstream of (i) growth factor (EGFR) mediated signals, (ii) upregulated RAS signals, and/or (iii) PI3-kinase mediated signals which activates MEK via RAF." (PMID 25425962, 2014). "EGFR has functions in the proliferation, migration, invasion and DNA damage repair processes of glioma cells, and aberrant signal transduction pathways are able to promote the growth, migration, angiogenesis and apoptosis of the tumor cells." (PMID 25364437, 2014). "In this study, we demonstrated that miR-566 is up-regulated in human glioma cell lines and inhibition of miR-566 decreased the activity of the EGFR pathway." (PMID 24650032, 2014). "Here show a dose- and time-dependent reduction of EGFR by hrEFEMP1 in one of the studied glioma cell lines, U251." (PMID 25594013, 2014). "We previously demonstrated that miR-21 is upregulated in glioma cells and that blocking its expression inactivates EGFR/Akt signaling in a PTEN-independent manner." (PMID 24650032, 2014). "To determine if there is a correlation between protein expression levels of EFEMP1 and EGFR in gliomas, we tested a tissue microarray (TMA) of astrocytic gliomas (N = 65) with antibodies for EGFR and EFEMP1." (PMID 25594013, 2014). "In the EFEMP1-low glioma subset (N = 101), EGFR showed a significant, unfavorable, patient prognosis, with HR = 2.1 and a 95% confidence interval = (1.3 – 3.4)." (PMID 25594013, 2014). "PDGFRα is another critical gene in glioma biology, as it is the second most frequently mutated TRK in GBM, following EGFR." (PMID 25380967, 2014). "In our previous studies, the EGFR antibody-conjugated liposomes were constructed for the selective delivery of sodium borocaptate and bioluminescence imaging in EGFR-overexpressing glioma." (PMID 25190023, 2014).
glioma (continued). "The molecular chaperone HSP90 is known to stabilize Akt and oncogenic forms of mutant EGFR, both of which contribute to the growth of a variety of cancers including gliomas." (PMID 24418474, 2014). "Pharmacological blockade of the EGFR by gefetinib had a rather modest inhibitory effect on glioma cell proliferation whereas pharmacological inhibition of SphK1 strongly blocked proliferation and induced apoptosis of a GBM-derived neurosphere cell line." (PMID 25309325, 2014). "The use of small-molecule inhibitors (Erlotinib, Gefintib, Labatinib, etc.)and monoclonal antibodies targeted against EGFR (Cetuximab and Panitututmab) is a common therapeutic strategy in several solid tumors, including gliomas." (PMID 24709958, 2014). "We have clarified that a miR-566 inhibitor blocks proliferation and invasion and accelerates apoptosis in glioma cells partially through the EGFR pathway." (PMID 24650032, 2014). "A glioma prognostic model also suggests EFEMP1's context-dependent oncogenic function in gliomas expressing low levels of EGFR." (PMID 25594013, 2014). "Dysregulated EGFR signaling through genomic amplification, observed in about 35–70% of GBMs, is an important contributing event to the oncogenesis of high grade gliomas." (PMID 25058589, 2014). "Amplification of the EGFR gene has been observed in colorectal cancer, pancreatic cancer, head and neck cancer, and glioma cases." (PMID 24662938, 2014). "In vitro and in vivo studies demonstrated that miR-566 inhibition deactivated EGFR/Akt signaling and slowed the proliferation of glioma cells." (PMID 24650032, 2014). "The EGFR pathway is activated in glioma and other human cancers, including lung, breast and colorectal." (PMID 24650032, 2014). "Other therapeutic agents against specific targets, including antivascular endothelial growth factor (VEGF) monoclonal antibody (bevacizumab) and epidermal growth factor receptor (EGFR) inhibitors, are also being used for disease control in glioma." (PMID 25162007, 2014). "After demonstrating that miR-566 deactivates the EGFR/Akt pathway, we examined miR-566’s function in glioma cell proliferation, invasion, apoptosis and cell cycle distribution." (PMID 24650032, 2014). "Wong and colleagues were the first to describe increased expression of the EGFR gene in gliomas with amplified EGFR as well as characterize the structural rearrangements of EGFR in malignant gliomas." (PMID 25268164, 2014). "Looking into well-known oncogenes and TSGs, we identified gains of EGFR in “de novo glioma pathway” (2 in LGG and 3 in HGG), as well as MDM2 (1 in LGG and 3 in HGG) and PTEN (1 in HGG), and losses of CDKN2A (2 in HGG)." (PMID 23451178, 2013). "Upon overexpression of miR-219-5p in glioma cell lines, there was consistent 40–50% reduction in the protein levels of EGFR in U138, U343 and U251 cell lines as assayed by western blotting." (PMID 23690991, 2013). "The epidermal growth factor receptor (EGFR) is often amplified and structurally rearranged in malignant gliomas, and the most common mutation is the EGFRvIII mutated glioma antigen." (PMID 23762610, 2013). "Oncogenic EGFR signalling networks are being described in glioma and were shown to be both robust and plastic, able to adapt to single molecule inhibition, and these are becoming targets for combination of EGFR and downstream pathway inhibitors." (PMID 23998913, 2013). "We found that loss of NOTCH3 inhibits glioma cell migration and invasion and demonstrated that NOTCH3 regulates glioma cell invasion via interaction with the EGFR/PI3K/AKT signaling pathway because NOTCH3 Knockdown indeed reduced the expression of EGFR." (PMID 24143218, 2013).
glioma (continued). "We have demonstrated that mir-146b reduces glioma cell motility and invasion, and that epidermal growth factor receptor (EGFR) mRNA is a binding-target for miR-146b silencing." (PMID 26082317, 2013). "Epidermal growth factor expression and stimulation of its cognate receptor (EGF/EGFR) have emerged as a pivotal signaling mechanism in high grade glioma." (PMID 23737783, 2013). "Consistent with the biological relevance of aberrant EGFR activation in glioma, GBM-SCs have been reported to be more dependent on Akt signaling than the non-CSC counterpart." (PMID 23355974, 2013). "Such an approach is clinically feasible as reported in two recent phase II trial: herein, recurrent gliomas were treated for 5 to 7 days with gefitinib or erlotinib before surgery and resected tissues were evaluated for EGFR-dependent phosphoproteins." (PMID 23874590, 2013). "Glioma cell invasion is promoted via the overexpression of receptors such as MET or EGFR, as well as downstream signaling through PI3K and MAPK pathways, and the Rho family of GTPases, among others." (PMID 24109588, 2013). "Reconstitution of wild-type PTPRK in malignant glioma cell lines suppressed cell growth and migration by inhibiting EGFR and β-catenin signaling and improved the effect of conventional therapies for glioma." (PMID 23696788, 2013). "The present study quantifies significant differences in delivery to the margins of orthotopic human glioma xenografts between two fluorescently labeled EGFR targeted proteins." (PMID 23593208, 2013). "It is also of note that the seemingly permanent, selective, and presumably advantageous genetic alterations (e.g., EGFR amplifications), are often lost from glioma cells as soon as these cells are separated from each other and placed in cell culture." (PMID 23508692, 2013). "We have previously reported on the tumor suppressive effect of EFEMP1 in GBM and EFEMP1's function in reducing the EGFR signaling activities in glioma cells." (PMID 24282558, 2013). "Further, the synergistic effect of cell subpopulation diversity on overall tumor growth is evident from the co-implantation experiments using glioma cells expressing the EGFR deletion mutant and wild-type EGFR." (PMID 24282558, 2013). "Not only EGFR gene amplification is the most common alteration in high-grade glioma, but also 50% of the EGFR amplified tumours express a constitutively active form of EGFR, which is required for glioma growth." (PMID 23998913, 2013). "Abnormalities on the EGFR and the EGFR-dependent signaling pathways are the most frequently reported in high-grade gliomas and affect all histological classes." (PMID 23874590, 2013). "Not only is de4 EGFR detectable in several human tumors, including glioma, prostate, and ovarian, but also its expression correlates with the malignant degree of glioblastomas." (PMID 24078813, 2013). "Cascades triggered or mediated by signaling pathways such as the Wnt/β-catenin, TGF-β, EGFR, and Notch pathways have been found to play important roles in glioma stem cell (GSC) development and/or maintenance of stemness." (PMID 24202447, 2013). "Although NBM culture, similar to serum spheroid culture, has been shown to preserve the genotype and phenotype of primary human gliomas, reports about the maintenance of EGFR amplification in derived cultures are contradictory." (PMID 24349039, 2013). "Our analyses on hallmark alterations in glioma genome show that LOH of 1p and 19q is more frequent in PDGFRA-high gliomas, and that EGFR amplification is more frequent in PDGFRA-low and PDGFRA-intermediate gliomas." (PMID 23630597, 2013). "Previous studies demonstrate that gliomas with deletion at both 1p and 19q and gliomas with EGFR amplifications are mutually exclusive regarding their cell(s) of origin, profiles of transcriptomic and genomic alterations, and clinical characteristics." (PMID 23630597, 2013). "A previous study has shown that glioma malignancy increases with EGFR amplification and overexpression." (PMID 23946790, 2013).
glioma (continued). "In primary gliomas, the frequency of amplification of EGFR has been reported around in 40% of the examined cases." (PMID 24294521, 2013). "Ectopic expression of PTPRK-wt in glioma cells showed significant reduction in the proliferation, migration and invasion rates compared to PTPRK variants possibly via negative regulation of EGFR and β-catenin signaling." (PMID 23696788, 2013). "STK17A resides on chromosome 7 approximately 12 MB from EGFR which is frequently amplified in gliomas." (PMID 24312360, 2013). "In contrast, an inverse significant correlation was identified with the EGFR gene amplification (P = 0.004) in both oligodendroglial tumors and the whole series of gliomas (P = 0.0005)." (PMID 24083241, 2013). "Epidermal Growth Factor Receptor (EGFR) is well validated as a primary contributor of glioma initiation and progression." (PMID 23782513, 2013). "All other attempts to establish EGFR amplified glioma cells in adherent serum conditions have failed and led to the assumption that EGFR amplification is “lost” during the culturing process." (PMID 24349039, 2013). "In two separate efforts, activated microglia from a murine glioma model demonstrated expression of EGFR as well as low levels of EGF secretion." (PMID 23737783, 2013). "Several studies have revealed that mutations in the epidermal growth factor receptor (EGFR) gene were associated with shorter intervals between relapses and a poorer survival rate for gliomas, and that EGFR expression is correlated with tumor progression." (PMID 23946790, 2013). "EGFR expression was significantly higher in the higher grade gliomas compared with the lower grade gliomas (P=0.025)." (PMID 23946790, 2013). "ADAM17 and EGFR have been reported to play important roles in glioma, and overexpression of ADAM17 promotes glioma invasiveness." (PMID 23076445, 2013). "In pediatric brain tumors, EGFR alterations are infrequent but our work and that of others suggests that activating BRAF mutations play a central role in both low and high grade glial tumors." (PMID 23592488, 2013). "Genetically, pediatric gliomas are more commonly associated with PDGFR-alpha aberrations compared to adult gliomas, which are more commonly associated with aberrations in EGFR signaling." (PMID 23383402, 2013). "Consistent with our expectations, transcripts for the ER chaperones GRP94 and GRP78 were upregulated in the U87MG and U87+EGFR gliomas, relative to normal mouse brain from healthy animals." (PMID 24039668, 2013). "Synergistically, microglia stimulate glioma cell invasion through epidermal growth factor receptor (EGFR) activation." (PMID 23864876, 2013). "Expression of phosphorylated proteins involved in the EGFR-dependent signaling pathways was analyzed in 10 glioma models." (PMID 23874590, 2013). "The EGFR is over-expressed in ~50–60% of gliomas, and EGFR increases with malignancy grade, and is required for maintenance of glioma growth." (PMID 23076445, 2013). "Neural stem cells have been used as substrate for transformation to high-grade glioma when tumour suppressors, p16INK4a and p19ARF, were knocked out and active forms of epidermal growth factor receptor (EGFR) were introduced." (PMID 23998913, 2013). "This complex polymer (np-PAMAM-Tat) was used to deliver anti-EGFR shRNA to subcutaneously-implanted gliomas, inhibiting EGFR/Akt signaling and slowing tumor growth." (PMID 24202446, 2013). "We analyzed the effect of DTX1 on the expression level of EGF receptor (EGFR), a receptor tyrosine kinase frequently over-expressed in gliomas." (PMID 23451269, 2013).
glioma (continued). "It was of our interest to see if the inhibition of PI3K/MAPK pathways and glioma cell migration achieved by the overexpression of miR-219-5p is because of its ability to target EGFR." (PMID 23690991, 2013). "EGFR immmunopositive staining was observed in 2 cases (22.2%) of grade I glioma, 25 cases (44.6%) of grade II, 37 cases (71.2%) of grade III and 31 cases (88.6%) of grade IV." (PMID 23946790, 2013). "Previously, we developed an immunoliposome conjugated with anti-EGFR antibody, which successfully targeted glioma cells for delivery of BSH and bioluminescence imaging in vitro and in vivo." (PMID 24069396, 2013). "We found that ectopic expression of miR-145 in U87 and U251n glioma cells caused decreased proliferation, migration and invasion with accompanying low protein expression of ADAM17 and EGFR." (PMID 23076445, 2013). "A recent study in glioma showed a possible cooperation between EGFR inhibition and temozolomide related reduction in tumor growth." (PMID 23696788, 2013). "According Mazzoleni and co-workers, cancer stem cells (CSC) isolated from glioma patients, need to express EGFR to promote experimental tumorigenesis and EGFR-expressing initiating cells display the most malignant phenotype." (PMID 23782513, 2013). "EphrinA5, a member belonging to the ephrinA subclass, negatively regulates EGFR by promoting c-Cbl binding and ubiquitination in glioma." (PMID 22860012, 2012). "MiRNA-146a was shown to be upregulated in epidermal growth factor receptor (EGFR) dysregulated cells in gliomas." (PMID 22523492, 2012). "The role of EGFR isoforms in glioma pathogenesis remains to be clarified, but their expression makes them potential targets of future diagnostic and therapeutic strategies." (PMID 22159595, 2012). "The EGFR gene has been reported as one of the major genes responsible for malignant progression and phenotype reversion of gliomas, and has been used as one of the most important therapeutic targets." (PMID 22662167, 2012). "Previous studies have shown that regulation of the epidermal growth factor gene (EGFR) pathway plays a role in glioma progression." (PMID 22662167, 2012). "Signal transducers and activators of transcription (STAT) is constitutively expressed in high-grade gliomas activated by epidermal growth factor receptor (EGFR)." (PMID 22984561, 2012). "A key target for glioma treatment is the EGFR that is highly expressed in different types of cancer including glioma." (PMID 22685651, 2012). "The EGFR gene was identified to be instrumental in glioma formation by EGFR transgenic rats (or mice) that developed cerebellar glioma." (PMID 22662167, 2012). "EGFR, for instance, is frequently activated in high-grade gliomas and comprises a receptor tyrosine kinase capable of phosphorylating β-catenin and thus activating wnt signalling." (PMID 22919349, 2012). "Membrane binding, intracellular and nuclear accumulation kinetics, and clonogenic survival assays were performed using the EGFR-expressing A431 epidermoid carcinoma and D247 MG glioma cell lines." (PMID 23107475, 2012). "Further, glass surfaces functionalized with anti-EGFR aptamers have been used to capture with high sensitivity and specificity human and murine glioma cells expressing EGFR." (PMID 22685651, 2012). "The presence of truncated EGFR isoforms in adult infiltrating gliomas must be considered in therapeutic management." (PMID 22159595, 2012). "The role of epidermal growth factor receptor (EGFR) signaling has been widely studied in both NSCs and glioma development." (PMID 22348397, 2012). "AON blocked EGFR on glioma cells as good as siRNA resulting in significant tumor growth inhibition in vivo and in vitro." (PMID 22355336, 2012). "Somatic alterations of the EGFR gene are common in glioma and influence several mechanisms of malignant transformation." (PMID 22662167, 2012).